TP53BP1 (tumor protein p53 binding protein 1)
Diseases named in the same sentence as TP53BP1 in open-access papers (continued):
Sharing a sentence is not in itself a finding about the gene and the disease.
squamous cell carcinoma of the head and neck (1 paper, 2014).
cancer (205 papers, 2005 to 2026). A tumor composed of atypical neoplastic, often pleomorphic cells that invade other tissues. "In order to realize these ambiguous findings, a meta-analysis was performed to assess the association between the TP53BP1 Glu353Asp (rs560191) polymorphism and susceptibility to cancer." (PMID 24603722, 2014). "So the results of studies concerning association between Asp353Glu (rs560191) polymorphism in TP53BP1 gene and risk of cancer are conflicting." (PMID 24603722, 2014). "In this meta-analysis, we had insufficient data to perform an evaluation of such interactions for the independent role of TP53BP1 Asp353Glu (rs560191) polymorphism in cancer development." (PMID 24603722, 2014). "These mutations in ATM and TP53BP1 could lead to the partial loss of DNA damage repair function observed in many human cancers, although further studies are required to confirm." (PMID 40340757, 2025). "Furthermore, loss of TP53BP1 function increases angiogenesis and is linked to poor prognosis in cancer." (PMID 39696035, 2024). "It is well known that SNPs may contribute to an individual’s susceptibility to cancer and TP53BP1 is a key component in the cellular response to DNA damage." (PMID 24603722, 2014). "However, studies investigating the relationship between TP53BP1 Glu353Asp (rs560191) polymorphism and cancer yielded contradictory and inconclusive outcomes." (PMID 24603722, 2014). "We found that the deletion of USP28 or TP53BP1 (53BP1) significantly reduced the sensitivity of several cancer cells to PLK4i treatment, mirroring the response observed in untransformed RPE1 cells." (PMID 41365927, 2025). "USP28 and TP53BP1 are also significantly enriched in genome-wide screenings for resistance to anti-cancer drugs (in 6 or 9 out of the 10 anticancer drug screens, for TP53BP1 or USP28, respectively)." (PMID 40082762, 2025). "Across cancers, we found that heterozygous loss events in XPC (2/5 tumor types), POLK (4/5), LIG4 (5/5), ATM (3/5), and TP53BP1 (3/5) were common in MYBL2 High tumors." (PMID 36358918, 2022). "We also identified other deletions associated with higher HRD in multiple cancer types, such as XRCC2/3 and BARD1 deletion in BLCA, TP53BP1, and RAD51 deletion in OV and LUAD, and CHEK1 deletion in TCGT and SKCM, etc.." (PMID 34572800, 2021). "Gonzalo’s lab demonstrated that 1,25(OH)2D stabilized TP53BP1 via its interaction with VDR and promoted DSBR through the inhibition of CTSL, which is important in cancer progression and is involved in TP53BP1 degradation." (PMID 32456160, 2020). "Mutation of TP53BP1 for instance, reverses the HR defect in BRCA1 mutant cancers and render these cancers resistant to PARP1 inhibition." (PMID 25852742, 2015). "Although the literature suggests that the two target genes (TP53BP1 and RPL8) and cancer development are associated, possible false positives may occur because the difference in temperature is too small." (PMID 40486861, 2025).
cancer (continued). "The SNPs for TP53BP1 gene may play an important role in the etiology of cancer because of a direct role of TP53BP1 in the cellular response to DNA damage." (PMID 24603722, 2014). "We have not found a sinificant association between TP53BP1 Asp353Glu (rs560191) polymorphism and cancer risk in overall population, but different ethnicity, study design, genotyping methods and cancer type would be responsible for the negtive conclusions." (PMID 24603722, 2014). "Notably, two proteins are associated with phosphosites significantly deregulated in all three PC cell lines as compared to PNT1A: TP53BP1, well-known cancer-related phosphosites downregulated in all three PC cell lines and DDX10, a potential new candidate, upregulated in PCa cell lines." (PMID 31675377, 2019). "In conclusion, this meta-analysis suggested that the polymorphism in TP53BP1 Asp353Glu (rs560191) gene could not be regarded as a genetic risk factor for cancer." (PMID 24603722, 2014). "Therfore, the SNPs of TP53BP1 may play an important role in the etiology of cancer." (PMID 24603722, 2014). "The TP53BP1 gene may be involved in the development of cancer through disrupting DNA repair." (PMID 24603722, 2014). "Among these candidate molecular targets, nine were significantly enriched in all three cohorts, and five of them (TP53BP1, RIPK2, EHMT2, IGFBP3, and HMOX1) have been reported to have cancer- and chemoresistance-promoting activities simultaneously." (PMID 35606881, 2022). "TAZ is a transcriptional coactivator upregulated in different types of cancer; its overexpression stimulates the expression of genes involved in NHEJ, such as TP53BP1 (53BP1), PRKDC (DNA-PKCs), and XRCC6 (Ku70), contributing to the radioresistant phenotype." (PMID 34900673, 2021). "Moreover, a number of target genes of miR-155 affect other cancer-related processes, such as cell growth and survival (CCND1 and GAB3), cell adhesion junction (ANKRD6 and SMAD2), proliferation (SOCS1 and STAT3), and apoptosis (TP53BP1)." (PMID 31744065, 2019). "The expression levels of FANCD2, TP53BP1, and RPA2 were statistically significantly elevated in HGD and in carcinomas, according to the results of non-parametric Friedman tests." (PMID 36061145, 2022).
tumor (172 papers, 2006 to 2025). "In the ATM signaling pathway, a high impact mutation (premature stop codon) in TP53BP1 (VAF = 0.012 in HCC cell line to VAF = 0.019 in HCC tumor) was identified." (PMID 40340757, 2025). "This partial restoration of homologous recombination, facilitated by factors like TP53BP1 loss, reduces tumor dependency on PARP-mediated repair, contributing to PARP inhibitor resistance." (PMID 40075604, 2025). "Case 15230 with BRCA1-mutated HGSC was found to have a missense TP53BP1 p.Lys1141Gln variant at a VAF of 46% in the post-PARPi tumour sample." (PMID 38072854, 2023). "In contrast to the MDM2-EP300 example, the most advantageous outcome for the tumor would seem to result if mutations at residues 181, 247 and 249 compromised both TP53BP1 and TP53BP2 interactions." (PMID 27043210, 2016). "qPCR analysis of the tumor tissue demonstrated that the expressions of DNA damage marker genes (TP53BP1, PARP1, and BRCA1), cGAS, STING, SEI1, and PD‐L1 were increased in melphalan or bortezomib treated mice." (PMID 40135791, 2025). "Analysis of cases enrolled in cohort A shows that patient 21557 was the only one with a SNV called in the TP53BP1 gene in all tumor biopsies but at T0." (PMID 35954363, 2022). "TP53BP1 recruitment can mediate the activation of autophagy by tumor self-DNA damage response." (PMID 33505990, 2020). "As an example, patient 21556, who carries a germline mutation in BRCA1, could be potentially eligible for PARPi therapy, but the targeted analysis of cfDNA at the time of diagnosis revealed the presence of two pathogenic variants in the TP53BP1 gene not detected in the tumor lesions analyzed." (PMID 35954363, 2022). "As a general comment, findings derived from the dynamic changes in the TP53BP1 suggest that most of the analyses of a single tumor biopsy, even at T0, are not adequate to predict the sensitivity or resistance profile to PARPi." (PMID 35954363, 2022). "SNP array identified frequent shared copy number events in all three tumor regions including FGFR1 amplification at chromosome 8p11.23 and classical CDK4, HMGA2 and MDM2 amplification at chromosome 12q13-15 region and deletion of TP53BP1 at chromosome 15q15." (PMID 26643872, 2015).
infection (23 papers, 2011 to 2025). The state of being infected such as from the introduction of a foreign agent such as serum, vaccine, antigenic substance or organism.
movement disorder (1 paper, 2025). Neurological conditions resulting in abnormal voluntary or involuntary movement, which may impact the speed, fluency, quality and ease of movement. "Recessively inherited cases with consistent neurodevelopmental and movement disorder phenotypes similar to CP were identified for four genes (HSPA12A, SLC7A1, TP53BP1, WWC1)." (PMID 41282771, 2025).
TP53BP1 also shares sentences with these, for which no sentence is quoted: prostate carcinoma (20 papers); osteosarcoma (17); glioma (14); glioblastoma (10); thyroid cancer (8); breast tumors (7); lymphoma (6); viral infection (6); head and neck cancer (5); leukemia (5); pancreatic cancer (5); Immunodeficiency (4); lupus (4); melanoma (4); squamous cell carcinoma (4); laminopathies (3); Ovarian tumors (3); rectal cancer (3); RIDDLE syndrome (3); sarcoma (3); synucleinopathy (3); T cell lymphoma (3); urothelial carcinoma (3); ataxia telangiectasia (2); esophageal SCC (2); Ewing sarcoma (2); follicular carcinomas (2); Hereditary breast cancer (2); lung adenocarcinoma (2); medulloblastoma (2).
A further 102 diseases each share a sentence with TP53BP1 in 2 papers or fewer.